JAK1 (Janus kinase 1)
Diseases named in the same sentence as JAK1 in open-access papers (continued):
Sharing a sentence is not in itself a finding about the gene and the disease.
endometrial cancer (continued). "In the present study, we demonstrated that knockdown or overexpression of JAK1 in endometrial cancer cell lines leads to changes in EC cell growth and migration potential in vitro." (PMID 36376931, 2022). "The targeted inhibition of JAK1 expression by miR-20a-5p can decrease proliferation and invasion and improve the adhesion ability of endometrial cancer cells." (PMID 35991559, 2022). "JAK1 frameshifts were significantly enriched in MSI-H endometrial cancers (38%; 50/131) versus microsatellite stable (MSS) endometrial cancers (<1%; 3/657), (P = 1.78 x 10−39, Fisher’s exact test)." (PMID 29121062, 2017). "Endometrial cancer cell lines with JAK1 frameshifts have been shown to be resistant to the effects of IFNγ, including a lack of growth arrest and a failure to up regulate antigen processing and presentation." (PMID 29121062, 2017). "This research shows that frameshift mutations in JAK1 frequently and almost exclusively occur in MSI endometrial cancers." (PMID 27213585, 2016). "Neither did subanalysis (e.g. in grade 3 cancers, or when analyzing only pelvic and distant recurrences) show a significant difference in outcome between JAK1 wildtype and mutant endometrial cancer patients." (PMID 27213585, 2016). "For JAK1 wildtype and mutant endometrial cancers, 10-year recurrence free rates were 84% versus 77%, respectively (P=0.301) and 10-year overall survival was 64.4% and 63.5% (P=0.716)." (PMID 27213585, 2016). "Taken together, these results provide evidence that CD146+CAFs could promote the progression of endometrial cancer by inducing angiogenesis and VM formation via the IL-10/JAK1/STAT3 pathway." (PMID 38459564, 2024). "Moreover, miR-20a-5 was recognized as a suppressor of endometrial cancer progression by targeting janus kinase 1 (Jak-1), belonging to a class of protein-tyrosine kinases involved in malignancies." (PMID 35563743, 2022). "The JAK1 pathway is involved in many types of human cancers, including hepatocellular carcinoma, gastric cancer, colorectal cancer, oral squamous cell carcinoma, and endometrial cancer." (PMID 36376931, 2022). "Thus, the previous association of these alterations with endometrial cancer is not unexpected since MSI is frequent in endometrial cancer and JAK1 frameshifts occur in 40–50% of MSI-H endometrial cancers." (PMID 29121062, 2017). "A separate study of MSI-H endometrial cancers also showed no prognostic value of JAK1 frameshift mutations in patients receiving standard clinical care." (PMID 29121062, 2017). "JAK1 frameshift alterations have been described mainly in the context of endometrial cancer." (PMID 29121062, 2017). "Survival analysis within the TCGA microsatellite unstable endometrial cancers with known JAK1 mutation status (n=30) showed neither a survival benefit for JAK1 wildtype tumors (data not shown)." (PMID 27213585, 2016). "It must be noted that it remains unclear why JAK1 mutations are limited to gynecological cancers and mainly to MSI endometrial cancer." (PMID 27213585, 2016). "To date, there is very little evidence for the functionality of JAK1 frameshift mutations in endometrial cancer." (PMID 27213585, 2016). "However, additional studies are required on the immune microenvironment of JAK1 mutant endometrial cancers (e.g. PD-L1 expression)." (PMID 27213585, 2016). "In conclusion, we confirmed the remarkably high frequency of JAK1 mutations and associations with impaired upregulation of antigen presenting machinery components in MSI endometrial cancers, which suggest a functional role for JAK1 in an intriguing tissue-specific manner." (PMID 27213585, 2016). "Tumors with JAK1 mutations had a lower score than wild-type tumors specifically for the antigen processing component (MHC score, mean difference −0.3, P = 0.01 by Welch’s t-test), indicating immune evasion, similarly to what has been observed in endometrial cancer." (PMID 28539123, 2017).
endometrial cancer (continued). "JAK1 mutations were associated with impaired upregulation of antigen presenting machinery proteins LMP7 and HLA class I. The association of JAK1 mutations with limited expression of the antigen presentation pathway was validated using RNAseq data of the TCGA MSI endometrial cancers." (PMID 27213585, 2016). "The mRNA level of CDH5 was significantly correlated with JAK1 and STAT3 levels in endometrial cancer." (PMID 38459564, 2024). "The 13 JAK1 mutant endometrial cancers showed significantly lower expression of TAP1 (2.1-fold, P<0.001), LMP7 (3.0-fold, P<0.001), and HLA class I (2.5-fold, P<0.001) in comparison to JAK1 wildtype endometrial cancers." (PMID 27213585, 2016). "However, JAK1 mutations and other mechanisms involved in impeding antigen presentation and expression of antigen processing machinery components in MSI endometrial cancers may interfere with new treatment regiments for MSI tumors such as the programmed death 1 inhibitor pembroluzimab." (PMID 27213585, 2016). "The functional implication of JAK1 in tumor immune evasion was analyzed by expression analysis of TAP1, LMP7, HLA class I and presence of CD8-positive T-cells in the MSI endometrial cancers." (PMID 27213585, 2016). "Previous reports have shown frequent JAK1 frameshifts in endometrial cancer but none were observed in CRC, another tumor type with an established MSI-H phenotype." (PMID 29121062, 2017). "Thus, unlike our previous finding in endometrial cancer where JAK1 frameshift was the predominant mechanism of the IFNγ-IRF1 pathway genetic defects, JAK2 gene deletion was the predominant mechanism of the IFNγ-IRF1 pathway genetic defects in NSCLC." (PMID 28977839, 2017).
glioma (17 papers, 2012 to 2025). A benign or malignant brain and spinal cord tumor that arises from glial cells (astrocytes, oligodendrocytes, ependymal cells). "In the case of high-grade gliomas, JAK1/2-STAT3 along with a hypoxia-induced pathway utilizing hypoxia-inducible factor 1α (HIF-1α) TF has been reported for enhancing the self-renewal capability of glioma stem-like cells." (PMID 40548119, 2025). "IL10 binds to its corresponding receptor, causing STAT3 phosphorylation through JAK1 and STAT2, which stimulates the proliferation of glioma cells." (PMID 35741689, 2022). "Glioma-associated DEGs DOCK6, ILK, MGMT, NOTCH4 were up-regulated and FGF10, JAK1, JUNB, RHOB were down-regulated uniquely in the mouse." (PMID 29352201, 2018). "Finally, our tissue-specific analyses highlight five candidate tissues (cerebellum, cortex, and the putamen, caudate and nucleus accumbens basal ganglia) and four genes (JAK1, STMN3, PICK1 and EGFR) which had causal evidence for affecting glioma risk in further research." (PMID 33504897, 2021). "In addition to CREB and NF1, previously established targets of miR-9 in glioma stem cells, such as CAMTA1 and JAK1/2, might contribute to the function of miR-9 in glioma cells, although further investigation will be required." (PMID 23185366, 2012). "A recent study indicated that the binding of T cells to glioma cells calls for the IFNγR signaling pathway (IFNGR1, JAK1 and JAK2) in which IFNGR1 was found necessary for this kind of cell-cell adhesion." (PMID 36309750, 2022). "Western blot was used to detect the phosphorylated forms of MAPK family members (ERK1/2, JNK and p38 MAPK), AKT and JAK‐STAT family members (JAK1 and STAT1) in glioma cells which transfected with NC and KLHDC8A siRNA." (PMID 32851798, 2020). "Results showed that expressions of IFNGR1 and JAK1 were significantly higher compared to the other three glioma cell types, but expression of JAK2 was not obviously different." (PMID 36309750, 2022). "HIF-1α combined with JAK1/2-STAT3 (Janus kinase 1/2-signal transducer and activator of transcription 3) axis could enhance the self-renewal of glioma stem-like cells." (PMID 35607406, 2022).
Arthritis (16 papers, 2010 to 2025). Inflammation of a joint. "This arthritis study utilized JAK1‐3i and observed the prevention of bone resorption through JAK inhibition over the same 7‐day experimental period as ours." (PMID 41041963, 2025). "Baricitinib, a JAK1/2 inhibitor, induced improvements in lupus rashes and arthritis in a phase 2 and a phase 3 RCT." (PMID 38899167, 2024). "Baricitinib, a JAK1/2 inhibitor originally used in arthritis treatment, is now showing potential in Alzheimer’s trials by suppressing inflammatory cytokines directly within the central nervous system." (PMID 39769374, 2024). "Baricitinib, a JAK1/2 inhibitor, demonstrated significant improvements in lupus rashes and arthritis in a phase 2 and a phase 3 randomised controlled trial, but the results were not replicated in another phase 3 trial." (PMID 37457579, 2023). "One phase II RCT (NCT02708095) demonstrated the efficacy of baricitinib (a JAK1/2 inhibitor) in alleviating arthritis in SLE patients." (PMID 32789005, 2020). "While both upadacitinib and tofacitinib demonstrated efficacy in a rat model of arthritis, the increased selectivity of upadacitinib for JAK1 resulted in a reduced effect on reticulocyte deployment and NK cell depletion relative to efficacy." (PMID 30886973, 2018). "Tofacitinib is a JAK3 inhibitor and demonstrates some JAK1 pathway inhibitory effects in mouse models of arthritis." (PMID 27379204, 2016). "Considering the resistance of her arthritis to anti-TNF therapy, the potential pathogenic mechanism behind the disease and the existing clinical indication for JAK1/2 inhibitor for arthritis, the patient was switched to baricitinib, with a good clinical response." (PMID 41249727, 2025). "It remains to be seen whether the proband will also manifest arthritis while receiving a JAK1/2 inhibitor." (PMID 32398023, 2020).
Autoimmunity (16 papers, 2012 to 2026). The occurrence of an immune reaction against the organism's own cells or tissues. "Applying this approach to a cohort of patients with suspected PIDD led to the identification of novel hyperactivating JAK1 variants and expanded the clinical spectrum of JAK1 GOF-associated disease to include autoimmunity and susceptibility to infections." (PMID 41136770, 2025). "Sporadic reports of JAK1 GOF variants with PIDD associated to autoimmunity or inflammation have significantly advanced our understanding of the molecular mechanisms underlying JAK/STAT activation, which is key for guiding targeted therapies." (PMID 41136770, 2025). "JAK1 promotes peripheral tolerance in autoimmunity through programmed cell death ligand 1 (PD-L1)-mediated regulatory T-cell induction." (PMID 41453319, 2025). "The other nodes of the network mainly contain genes/proteins related to autoinflammatory/autoimmunity, such as JAK1, STAT3, STAT5B, IL10RA, and IL10RB, with SOCS3 as a hub." (PMID 39359477, 2024). "Here we report the rational discovery and preclinical development of a JAK1-selective siRNA for the modulation of autoimmunity in the skin." (PMID 37925520, 2023). "The goal of this study is to determine if the JAK1/JAK2 inhibitor baricitinib impairs type 1 diabetes autoimmunity and preserves beta cell function." (PMID 35606820, 2022). "Our lab has successfully employed JAK1/JAK2 inhibitors to reverse established autoimmunity in NOD mice." (PMID 35606820, 2022). "Pathway crosstalk analysis for potential therapeutic intervention identified a network of 53 interconnecting genes, including genes that are already therapeutic targets in AS and other autoimmune conditions, such as JAK1 and TYK2, alongside yet unexplored genes." (PMID 37388915, 2023). "Future work using a skin disease model with milder autoimmunity that more closely resembles human disease progression may be helpful for evaluating the disease-reversing effect of the JAK1 siRNA." (PMID 37925520, 2023). "Additionally, JAK1 inhibitors are under investigation for treatment of cancers and autoimmunity." (PMID 31680865, 2019). "This section describes PID with autoimmunity including monogenetic diseases of the immune system affecting self-tolerance by thymic impairment (e.g., APECED) and/or other T-lymphocyte function deficiencies (ZAP70), syndromic diseases (JAK1 GOF) or metabolic diseases (Prolidase deficiency)." (PMID 31799221, 2019). "Thus, IL-15/IL-15Rα activates the JAK1/JAK3 and STAT3/STAT5 pathways to induce proliferation of T and NK cells, and this mechanism could limit exposure to circulating IL-15, that contributeS to the risk of autoimmunity." (PMID 22888423, 2012). "Finally, the JAK1/2 inhibitor ruxolitinib, which blocks the JAK kinase upstream from STATs, has been successfully used to ameliorate CMC and autoimmunity in several STAT1 GOF patients." (PMID 37358695, 2023). "These inhibitors specifically target γc chain receptor signaling while sparing the signaling pathways of immunoregulatory cytokines, such as IL-10R (TYK2/JAK1), IL-27R (JAK1/JAK2), and IL-35R (JAK1/JAK2), which may contribute to preventing autoimmunity in the hair follicle." (PMID 41488086, 2025). "Alternatively, JAK1 might not be the primary pathway that leads to the emergence or exacerbation of autoimmune conditions." (PMID 39258033, 2024). "Surprisingly, novel therapies, like JAK1/2 inhibitors, showed not only the potency to suppress the enhanced STAT1 phosphorylation in CD4+ T lymphocytes but may also improve clinical outcome in both immunodeficiency and autoimmunity features." (PMID 28348565, 2017).
lung adenocarcinoma (16 papers, 2016 to 2024). A carcinoma that arises from the lung and is characterized by the presence of malignant glandular epithelial cells. "For example, in KRAS-mutated lung adenocarcinoma cells, the secretion of proinflammatory cytokines, including interleukin-6, activates JAK1 and JAK2 through glycoprotein 130 in an autocrine loop, thus, contributing to malignant progression." (PMID 38706597, 2024). "Low expression of JAK1 is closely associated with immune infiltration and poor prognosis in lung adenocarcinoma." (PMID 37976123, 2023). "In subgroup analysis, high JAK1 expression was associated with a preferable prognosis in lung adenocarcinoma (OS: HR, 0.74, 95% CI from 0.58 to 0.95, log-rank P = 0.017), not squamous cell carcinoma." (PMID 34587898, 2021). "For the mutations in JAK1, 3 of 12 are loss-of-function mutations (frame shift or nonsense) and the S816* mutation has been reported in a lung adenocarcinoma sequencing data set21." (PMID 30181556, 2018). "In a database analysis study of lung adenocarcinoma transcriptome profiles, JAK1 expression was positively correlated with immune-cell infiltration, suggesting a potential role of JAK1 in the immune response." (PMID 38115208, 2023). "The potential molecular mechanism of JAK1 was determined by conducting a GSEA using the Cancer Genome Atlas Lung Adenocarcinoma (TCGA-LUAD) dataset." (PMID 33323549, 2020). "Our findings suggest thatDEGs encoding subunits of NADH, PRIM1, MCM3, MAPK1, STAT3, RAF1, and JAK1 might beassociated with the development of lung adenocarcinoma." (PMID 26840709, 2016). "However, the potential role of JAK1 in immune infiltration and prognosis of lung adenocarcinoma (LUAD) remains unclear." (PMID 33323549, 2020). "Based on the GSE164789 lung adenocarcinoma single-cell RNA-seq cohort, the variations in the expression of STAT3 and JAK1, the core genes in the IL6-JAK-STAT3 pathway, were calculated based on the developmental trajectory of MDSCs." (PMID 39049031, 2024). "ERS-related autophagy is also observed in lung adenocarcinoma, where interferon gamma (IFN-γ) induces ERS and UPR in lung adenocarcinoma cells by activating the JAK1/2–STAT1 and AKT–mTOR signaling pathways." (PMID 39080273, 2024). "It has been reported that absence of JAK1 expression induced human lung adenocarcinoma unresponsive to IFN-γ." (PMID 30837996, 2019).
colitis (15 papers, 2019 to 2026). Inflammation of the colon. "This hypothesis is in line with findings from Lu, Y, who demonstrated that Monotropein could inhibit colitis-associated cancer through the VDR/JAK1/STAT1pathway, influencing macrophage polarization." (PMID 39513122, 2024). "At the same time, another study demonstrated that TRIM27 could induce colitis to promote the tumorigenesis of colitis-associated cancer by recruiting gp130 and JAK1 to activate the IL6-STAT3 signaling pathway." (PMID 36200036, 2022). "Taken together, our work suggests that oral administration of cimifugin ameliorates DSS-induced colitis and its associated lung inflammation, which is associated with its inhibition of chemokine release, reduction of M1 macrophage infiltration and down-regulation of JAK1/STAT1 protein expression." (PMID 40666519, 2025). "Leucrose, a natural sucrose isomer, suppresses DSS-induced colitis in mice by regulating macrophage polarization via JAK1/STAT6 signaling." (PMID 35663931, 2022). "The present study investigated the mechanism underlying curcumin treatment of IBD by observing the number of naïve, TEM, and TCM cells and the expression levels of related proteins in the JAK1/STAT5 signaling pathway in mice with colitis." (PMID 33597887, 2020). "For example, JAK1 inhibitor Filgotinib was approved for UC treatment optimized via a combination of virtual kinase selectivity profiling, cytokine suppression in co-cultured T-cell/epithelial systems, and targeted efficacy testing in murine colitis models." (PMID 41155651, 2025). "The results indicated that curcumin could effectively inhibit the activation of the JAK1/STAT5 signaling pathway in DSS-induced experimental colitis." (PMID 33597887, 2020). "In DSS-induced colitis in mice, AED at 10 μg/mL suppressed pro-inflammatory cytokine production and inhibited JAK1/STAT3 signaling." (PMID 42279653, 2026). "Luteolin-7-glucopyranoside exhibits antioxidant and anti-inflammatory properties by modulating the JAK1/STAT6/SOCS1 pathway and alleviating inflammatory diseases, such as colitis." (PMID 40283142, 2025). "Macrophages were affected by the JAK1 selective kinase inhibitor and pan-JAK inhibitor tofacitinib in an experimental colitis model." (PMID 36042351, 2022). "The protein levels of JAK1, JAK3, and STAT5 were downregulated in mice with colitis after curcumin treatment, indicating that curcumin inhibited JAK-STAT signal activation." (PMID 33597887, 2020).